SALL4 (spalt like transcription factor 4)
Diseases named in the same sentence as SALL4 in open-access papers (continued):
Sharing a sentence is not in itself a finding about the gene and the disease.
tumor (continued). "pSTAT3 showed consistent nuclear staining throughout the sample (brown), and SALL4 staining was localized predominantly to the nuclei of tumor cells but was mostly cytoplasmic in the proliferative endothelium (brown)." (PMID 27617262, 2016). "We then detected the influence of SALL4 knockdown in the pathways that critically regulate tumour growth and metastasis." (PMID 27819668, 2016). "Taken together, these HCC patients with higher serum SALL4 expression had poor prognosis both in tumor recurrence and overall survival." (PMID 24860834, 2014). "Here, we report that high SALL4 serum levels are a potential novel biological biomarker correlating with tumor recurrence and poor survival of the HCC patients." (PMID 24860834, 2014). "Next, we had followed up these 64 HCC patients with SALL4 positive serum for two years to determine the relationship with tumor recurrence and overall survival." (PMID 24860834, 2014). "Collectively, these data indicated that SALL4 expression in tumor tissues has high degree of tumor selectivity and complexity." (PMID 24860834, 2014). "These HCC patients showing high SALL4 serum levels had poor prognosis, evidenced by both tumor recurrence and overall survival rate." (PMID 24860834, 2014). "Usually these studies about the role of SALL4 were focused on tumor cell lines and tumor tissues investigating carcinogenesis and treatment." (PMID 24860834, 2014). "It has been shown that all types of testicular GCTs express SALL4 protein in correlation with degree of tumor differentiation and suggested that SALL4 is essetial for the maintanance of poorly differentiated status." (PMID 23363002, 2013). "Significant overexpression of SALL4 mRNA was detected in 40 of 46 of tumor specimens (87%, P < 0.0001)." (PMID 23363002, 2013). "SALL4 expression was significantly correlated with tumor cell metastasis to lymph nodes, especially in moderately-differentiated tumor samples (P < 0.05)." (PMID 23363002, 2013). "SALL4 expression in fresh tumoral and distant tumor-free tissues from 46 colorectal samples was compared by real-time polymerase chain reaction (PCR)." (PMID 23363002, 2013). "Transcription factors that have been shown to maintain the pluripotency and self-renewal of ES cells and tumor cells include Oct4, Nanog, Sox2, Rex1 and Sall4." (PMID 23049777, 2012). "The mechanism of SALL4 in the pathogenesis and its role in the prognosis of this tumor need further investigation." (PMID 22848863, 2012). "MMMT should be considered in the differential diagnosis when tumor is positive for both SALL4 and/or glypican-3." (PMID 22848863, 2012). "MMMT should be included in the differential diagnosis when a tumor is positive for SALL4 and/or glypican-3." (PMID 22848863, 2012). "Sall4, Grb2, β-catenin, and Stat3 are known to be expressed in tumor cells and their roles in cancer has been already studied." (PMID 20950440, 2010). "Immunohistochemically, these tumours might still harbour positive staining for TGCT markers such as SALL4, but they are particularly positive for markers typically found in the somatic counterpart (e.g. muscle markers in rhabdomyosarcoma)." (PMID 41384700, 2026). "Moreover, SH6 treatment led to a significant 87% tumor growth inhibition of SALL4+ patient-derived xenografts and demonstrated good bioavailability in pharmacokinetic studies." (PMID 40369156, 2025). "All tumor cells were SALL4+, a general GCT marker (SOX2 inlay)." (PMID 40025812, 2025). "The tumor cells also demonstrated heterogeneous positivity for SALL4 by immunostaining." (PMID 40657563, 2025). "In summary, the similar effects of gain and loss of function for both Sall4 and Bmi1 in AY-CCA suggest that BMI1 may act as a downstream effector of SALL4 in AY-CCA tumor development." (PMID 40932240, 2025). "Histologically, HA-tagged (myrAKT) tumor regions were drastically reduced in Sall4 KOhepΔ livers." (PMID 40932240, 2025).
tumor (continued). "Moreover, conflicting reports on SALL4 expression in CCA raise the possibility that its role has been underappreciated because of diagnostic challenges and tumor heterogeneity." (PMID 40932240, 2025). "Next, we investigated the role of SALL4 on SHH-dependent tumor growth." (PMID 38062245, 2024). "Remarkably, inhibition of SALL4 arrests tumor growth in vitro and in vivo." (PMID 38062245, 2024). "The function and mechanism of SALL4 in gastrointestinal tract cancers require further investigation, which may provide new insights into tumor therapy." (PMID 38584262, 2024). "SALL4 regulates multiple caspase family members in tumor cells." (PMID 38584262, 2024). "As an oncogene, SALL4 has been found to be abnormally elevated in both tumor tissues and cells." (PMID 38584262, 2024). "Although thalidomide can target several substrates, our findings suggest that the thalidomide-dependent degradation of SALL4 may represent one mechanism contributing to the anti-tumor effects of this drug in SHH-MB." (PMID 38062245, 2024). "In vitro studies have identified miR-3622a-3p as a tumor suppressor by targeting SALL4." (PMID 38584262, 2024). "Whether this inhibitory effect on tumor cells is due to SALL4 targeting, as observed in ESCC, requires further exploration." (PMID 38584262, 2024). "Several studies have established that SALL4 overexpression stimulates proliferation, development, invasion, and migration in cancers, highlighting its critical oncogenic role in gene transcription and tumor growth." (PMID 39001344, 2024). "In these patients, serum SALL4 levels were related to tumor recurrence and survival." (PMID 36979716, 2023). "Of note, the expression of SALL4 was higher in CAF than tumor cells (P = 0.008)." (PMID 36587397, 2023). "We found that the upregulation of SALL4 in STAD was positively correlated with tumor progression." (PMID 37525212, 2023). "The results revealed that SALL4 was expressed in both tumor cells and CAF." (PMID 36587397, 2023). "Studies have shown that SALL4 protein expression is negatively regulated by miRNAs (miRNAs) belonging to the Let-7 family, particularly by miR-98, which leads to a reduction in tumour cell proliferation, indicating that miR-98 acts as a tumour suppressor that inhibits SALL4 protein expression." (PMID 37559082, 2023). "Thus, understanding the functions and mechanisms of SALL4 can provide novel insight into how SALL4 can be targeted in tumor therapies." (PMID 35216168, 2022). "Additionally, SALL4 regulates tumor progression correlated with the immune microenvironment involved in the TNF family and gene expression through epigenetic mechanisms, consequently affecting hematopoiesis." (PMID 35216168, 2022). "Moreover, SALL4 promotes tumor migration and mammosphere formation in vitro and tumorigenicity in vivo in BC by inducing mesenchymal markers such as vimentin by directly binding to its promoter." (PMID 35216168, 2022). "This compound demonstrated tumor suppressive role both in vitro and in vivo on SALL4 high cells." (PMID 36010677, 2022). "Moreover, invasion and migration reduced upon SALL4 knock down in vitro and size and weight of the transplanted tumor reduced significantly in the mouse model." (PMID 36010677, 2022). "Among them, there were luminal B (n = 127), basal-like (n = 98), luminal A (n = 231), HER2+ (n = 58) and normal-like tumor samples (n = 9), which showed the highest expression of SALL4 (p-value = 0.0013) in HER2-enriched tissue samples followed by luminal A, luminal B and basal-like subtypes." (PMID 36362083, 2022). "Moreover, SALL4 regulates gene expression through epigenetic mechanisms, then affecting tumor progression." (PMID 35216168, 2022). "SALL4 exerts its tumor promoting effects through apoptotic pathways." (PMID 35619068, 2022). "Increasing evidence indicates that SALL4 could be a potential target for tumor treatments and a clinically diagnosed idiosyncratic biomarker in different tumors." (PMID 35216168, 2022).
tumor (continued). "SALL4 influences tumor survival by regulating multiple caspase members." (PMID 35216168, 2022). "SALL4 played a vital role in tumor proliferation, invasion, and tumor EMT and may be a novel target for COAD." (PMID 35692499, 2022). "Moreover, from the cell sphere formation, it can be intuitively seen that the tumor-suppressive effect of zebularine can be rescued by anti-miR-497-5p and overexpressed SALL4 (P < 0.001)." (PMID 34732693, 2021). "Our study further confirmed that the expression of CTA and SALL4 in HCC tumours might promote antitumour immune surveillance and facilitate postoperative recovery." (PMID 34496797, 2021). "Moreover, co-expression of LINC-ROR and SALL4 in tumor samples was significantly correlated with moderately differentiated (p = 0.05)." (PMID 33745265, 2021). "In addition, SALL4 expression in tumor cells was more frequent in male patients (P = 0.001) and in older patients (P = 0.012)." (PMID 33644042, 2021). "SALL4 expression in adults is restricted to spermatogonia, and is required for long‐term maintenance of SSCs by repressing expression of Foxl1 and Dusp4, two tumour suppressor genes that inhibit SSCs growth and self‐renewal." (PMID 34296486, 2021). "In addition, the flavonoid chrysin treatment of CT29 murine CRC cells decreased SALL4 expression, resulting in apoptosis induction associated with increased BAX levels and caspase 3/9 activity and with a decrease in tumor size in allograft assays." (PMID 34944911, 2021). "On the other hand, SALL4 could impact the tumor microenvironment and support tumor progression by affecting the HCC exosome content." (PMID 34944911, 2021). "In addition to SALL4, other mechanisms mediating the tumor-suppressive effect of miR-98 in HCC have been proposed." (PMID 34573282, 2021). "Tumor SALL4-positive was also more common in Lauren mixed-type GC (P < 0.001)." (PMID 33644042, 2021). "This high expression of SALL4 positively correlated with tumor size and lymphatic metastasis." (PMID 34944911, 2021). "The tumor suppressor gene PTEN has been identified as a key downstream target of SALL4, as SALL4 directly interacts with the nucleosome remodeling and histone deacetylation (NuRD) complex and can be recruited to the promoter region of PTEN and other genes, inducing transcriptional repression." (PMID 34573282, 2021). "Interestingly, the expression level of LINC-ROR decreased in tumor specimens with a low level of SALL4 expression (p < 0.05) compared to SALL4 overexpression samples (p = 0.92)." (PMID 33745265, 2021). "Meanwhile, with the expansion of our knowledge about miRNA regulation machinery and advances in RNA therapeutic delivery, a better understanding of the microRNA/SALL4 interaction in tumor biology may help guide the development of targeted treatment." (PMID 34573282, 2021). "We further assessed the effects of SALL4 and miR-497-5p on tumor progression in vivo." (PMID 34732693, 2021). "In the context of ccRCC, SALL4 promoted tumor vascularization by recruiting endothelial cells." (PMID 32513235, 2020). "Moreover, SALL4 expression varied depending on tumor invasion depth, lymph node status, distant metastasis, histological grade and AJCC stage." (PMID 32513235, 2020). "Thus, SALL4 plays an essential role in regulating tumorigenesis, tumor growth and tumor progression." (PMID 32098783, 2020). "Consistent with our previous reports, SALL4 knockdown inhibited tumor growth in both models." (PMID 32489324, 2020). "We found that upregulated SALL4 in ccRCC positively correlated with tumor progression." (PMID 32513235, 2020). "For example, STAT3, KLF4, Sal‐like protein 4 (SALL4), SOX‐2, and CTNNB1 are aberrantly expressed in BCs, and their high expression is associated with tumor progression and poor prognosis." (PMID 31709755, 2020). "Overexpression of SALL4 contributes to tumor growth in breast cancer." (PMID 32719361, 2020). "Previous studies have identified SALL4 as a tumor-promoting oncogene." (PMID 32513235, 2020).
tumor (continued). "There are few studies on the role of SALL4 in tumor metabolism." (PMID 32489324, 2020). "The tumor was positive for p40, Sal-like protein 4 (SALL4), and human chorionic gonadotropin (hCG)." (PMID 30959361, 2019). "By dynamically recruiting each specific epigenetic factor, SALL4 expression can directly affect DNA and histone methylation/acetylation status at important genes that control hematopoietic differentiation, apoptosis, tumor induction or suppression." (PMID 29308206, 2018). "SALL4 expression showed significant differences between normal and tumor tissues of NSCLCs." (PMID 29691367, 2018). "In mammals, expression of SALL4 has been primarily detected in ESCs and adult tissue “stem-like” cell populations, where it acts as a core controller regulating cell “stemness” in developmental events and also in tumor growth." (PMID 29308206, 2018). "For example, in NB4 AML cells transduced with lentiviral SALL4, there was an overall increased percentage of DNA methylation (a range of 1.2 to 2-fold) at various CpG sites of tumor suppression gene PTEN promoter, which co-relates with a down-regulated gene transcription." (PMID 29308206, 2018). "Moreover, there was significant correlations between SALL4 expression and tumor differentiation and depth of invasion." (PMID 30579343, 2018). "An advantage of IHC is the possibility to evaluate the expression of a marker in the whole tumor section allowing the detection of even a focal positivity in heterogeneous tumors (as it could be for SALL4, a stemness-related marker)." (PMID 28160555, 2017). "Therefore, in our opinion, the best method to assess SALL4 presence in cancer is standardized IHC on whole tumor section." (PMID 28160555, 2017). "Moreover, SALL4 expression was enriched in the side population (SP) of tumor cells, implicating its roles in cancer initiation and drug resistance." (PMID 28974232, 2017). "Growing evidence suggests that SALL4 plays a vital role in tumor progression and metastasis." (PMID 27329034, 2016). "Xenograft tumor models showed that silencing of SALL4 decreased the ability to form tumors in vivo." (PMID 27329034, 2016). "SALL4 is critically involved in tumour growth, metastasis and therapy resistance." (PMID 27819668, 2016). "Once SALL4 was activated, it may trigger downstream target gene Wnt3a to promote tumor progress and metastasis." (PMID 27329034, 2016). "SALL4 knockdown dramatically inhibited tumor growth compared to scramble shRNA control group." (PMID 27705911, 2016). "However, further mechanisms of SALL4 affecting tumor growth and drug sensitivity of tumor to chemotherapy are required to investigate." (PMID 26935744, 2016). "Moreover, SALL4 expression was closely correlated with the stage of tumor (P = 0.0477) and lymph node metastasis (P = 0.0068)." (PMID 27329034, 2016). "The tumor suppressor PTEN has been shown to be repressed among the target genes by SALL4." (PMID 27610139, 2016). "The stronger expression of SALL4 was inversely correlated with tumor differentiations." (PMID 25346886, 2014). "Interestingly, our results for the first time indicated that HCC patients with high SALL4 serum levels had poor prognosis, proved by both tumor recurrence and poor overall survival rate." (PMID 24860834, 2014). "High serum levels of SALL4 protein could be used as a novel biomarker predicting tumor recurrence and poor survival rate of patients afflicted with HCC." (PMID 24860834, 2014). "The stronger expression of SALL4 was inversely correlated with tumor differentiation." (PMID 25346886, 2014). "In CRC samples, overexpression of SALL4 may have a fundamental role in tumor cell survival by transcriptional repression of pro-apoptotic genes such as PTEN." (PMID 23363002, 2013). "In such tumor samples, SALL4 expression was significantly higher in younger than older patients." (PMID 23363002, 2013).
tumor (continued). "Immunohistochemistry results indicated that high expression of KPNA2 expressed significant association with a poor tumor grade, an advanced FIGO stage, recurrence and uncontrolled, resistance/refraction to initial chemotherapy, and SALL4 level in these patients." (PMID 22962582, 2012). "The IH tumor spheres also resembled induced pluripotent (iPS) stem cells that have been generated from fibroblasts in our laboratory, and also express SALL4." (PMID 22192404, 2011). "Due to diagnostic challenges—germ cell phenotype, SALL4 positivity, weak PAX8 positivity suggesting mediastinal germ cell carcinoma, while clinical features argued for a poorly differentiated epithelial thoracic malignancy—the case was presented to the tumor board for further evaluation." (PMID 40421964, 2025). "In the ANRAS and KP53 models, loss of Sall4 had no significant impact on tumor development." (PMID 40932240, 2025). "However, there are still some scientific hypotheses to be tested regarding whether SALL4 is a therapeutic target, such as different tumor microenvironments and drug resistance." (PMID 35216168, 2022). "Therefore, SALL4 plays a critical oncogenic role in gene transcription and tumor growth." (PMID 35216168, 2022). "Moreover, SALL4 has been found to act critically in tumor genesis, progression, and metastasis." (PMID 35692499, 2022). "However, our results propose that concomitant dysregulation of LINC-ROR and SALL4 in transcript level may have a potential role in tumor initiation and invasion of GC." (PMID 33745265, 2021). "The results showed that six genes (BOLA3-AS1, AC124067.4, AL161772.1, SALL4, PHYHIPL, and TNFSF11) were significantly associated with the COAD immune subtype (p < 0.05), indicating that these seven genes could modulate tumor immune functions at the genetic level." (PMID 34746134, 2021). "Moreover, we indicated a significant correlation between concomitant expression of LINC-ROR and stemness transcriptional factor SALL4 with clinicopathological features, including H. pylori infection, depth of tumor invasion, tumor location, differentiation, tumor grade, and sex in gastric tissues." (PMID 33745265, 2021). "In addition, we found that SALL4 could exert its tumor-promoting effect via modulating Akt/GSK-3β axis and VEGFA expression." (PMID 32513235, 2020). "Furthermore, the tumor included SALL4-positive germ cell-like cells." (PMID 32972454, 2020). "Up-regulation of the SPP1, miR-122, SRPX2, ADH1B, miR-21, SALL4 and PRAP1 genes, as well as down-regulation of miR-378e have been previously associated with an increased tumor cell migration capacity among sCRC, greater tumor progression potential, a metastatic phenotype and inhibition of apoptosis." (PMID 29296198, 2017). "Loss of function studies showed a key functional role of SALL4 in sustaining the survival, proliferation and tumorigenicity of HCCs; blocking of SALL4-corepressor interactions released suppression of PTEN expression and elicited an inhibition of tumor formation in xenograft tumor models." (PMID 28930164, 2017). "Thus, SALL4 expression is lower in tumor cells of older patients than younger ones." (PMID 23363002, 2013). "A small minority of tumor cells were convincingly positive for HMB45, and rare cells stained with SALL4, CD117, glypican‐3, myogenin, desmin, and synaptophysin." (PMID 40610013, 2026). "Immunohistochemical analysis revealed positive markers for SALL4, CD117, and CD56 in the tumor cells." (PMID 40832615, 2025). "Immunohistochemistry demonstrated positivity of the malignant yolk sac component for SALL4 (Sal-like protein 4), Glypican-3, and AFP, which confirmed yolk sac tumor differentiation." (PMID 41281142, 2025). "While residual tumor cells were observed in the gastric tumor, contrary to the liver tumors, both AFP and SALL4 were positive." (PMID 40657563, 2025). "Liver metastasis tends to have lower expression of SALL4 and ZNF770 compared to the primary tumours." (PMID 40241172, 2025).